MPO (myeloperoxidase)
Diseases named in the same sentence as MPO in open-access papers (continued):
Sharing a sentence is not in itself a finding about the gene and the disease.
coronary artery disease (continued). "In addition, MPO is closely associated with coronary artery disease, rheumatoid arthritis, asthma, cerebral ischemia–reperfusion injury, interstitial lung disease, and cancer." (PMID 39340342, 2024). "Moreover, MPO is considered an important inflammatory indicator of inflammatory responses, especially in the heart and coronary diseases associated with ischemic–reperfusion lesions." (PMID 36835008, 2023). "Elevated levels of MPO are predictors of coronary artery disease and the risk of MI." (PMID 35883722, 2022). "In patients with suspected coronary artery disease, a positive association between MPO-DNA complexes was reported with both the number of atherosclerotic coronary vessels and the occurrence of major adverse cardiac events, suggesting a relationship between NETs levels and unstable plaques." (PMID 35679310, 2022). "Moreover, serum MPO levels and activities correlated significantly with these indices of coronary artery disease severity after adjustment for other risk factors." (PMID 36404308, 2022). "For example, elevated levels of leukocyte- and blood-MPO are associated with the presence of coronary artery disease (CAD) and plasma MPO may predict the long-term risk of cardiovascular mortality in patients with CAD." (PMID 33916434, 2021). "MPO is associated with vascular dysfunction and underlies the pathophysiology of numerous vascular inflammatory diseases including arteriosclerosis and coronary artery disease." (PMID 34737733, 2021). "Furthermore, high circulatory MPO levels are associated with an increased risk of atherosclerosis, ischemic heart disease, and myocardial infarction (MI)." (PMID 35052529, 2021). "Indeed, elevated levels of MPO have been associated with coronary artery disease (CAD) and predict risk in acute coronary syndromes." (PMID 32754070, 2020). "Additionally, MPO-expressing macrophages have been implicated in the pathogenesis of acute coronary syndrome and SNPs located in the MPO promoter (the MPO-463G/A and -129G/A polymorphisms) have been shown to correlate with coronary artery disease." (PMID 33081376, 2020). "Plasma MPO levels have been associated with coronary artery disease." (PMID 26648662, 2015). "Additional evidences of the role of MPO in vascular pathology come from population studies, where elevated circulating levels of this enzyme in an initially healthy population predicted the risk of future coronary heart disease." (PMID 25814781, 2015). "Furthermore, plasma levels of myeloperoxidase (MPO) and MPO-DNA complex correlate with a risk of coronary artery disease and other major adverse cardiac events suggesting that NETs, and associated biomarkers can be used to predict a risk for atherosclerotic disease burden and events." (PMID 35433860, 2022). "However, less is known on the role of MPO in individuals without symptomatic CVD, but epidemiologic studies demonstrate that MPO may predict future risk of coronary artery disease." (PMID 32754070, 2020). "Clinical studies have shown that elevated blood MPO level was closely related to higher risk of coronary artery disease (CAD)." (PMID 26451069, 2015). "We investigated the association between myeloperoxidase gene -463G > A polymorphism and premature coronary artery disease (CAD) in two Chinese population samples: 229 patients and 230 controls." (PMID 21637677, 2009). "To date, several studies have shown that the -463G/A, -129G/A, -V53F, -A332V, and -638C/A SNPs and MPO levels are risk factors in coronary artery disease (CAD)." (PMID 21637677, 2009). "Our findings, along with previous studies, suggest that free MPO levels correlate with membrane-bound MPO in coronary artery disease." (PMID 40252642, 2025). "Multiple lines of evidence suggest an association between MPO and cardiovascular disease (CVD) including coronary artery disease, congestive heart failure, myocardial ischemia/reperfusion-related injury." (PMID 36896463, 2023).
coronary artery disease (continued). "MPO levels have been reported to be higher in patients with coronary artery disease (CAD) and can predict future cardiovascular events, even after correction for traditional risk factors and CRP." (PMID 37168278, 2023). "Myeloperoxidase (MPO) is currently thought of as a novel inflammatory biomarker in acute coronary syndrome and ischemic heart diseases." (PMID 36248416, 2022). "In the cited study the authors also observed a correlation between MPO levels and the progression of ischemic heart disease." (PMID 36463116, 2022). "MPO is an enzyme primarily produced by neutrophils that plays a key role in the pathophysiology of coronary artery disease, congestive heart failure, arterial hypertension, and other cardiovascular diseases." (PMID 36551214, 2022). "In human atherosclerotic plaques of coronary artery disease, catalytically active MPO protein and its oxidation products were detected in macrophages, nearby the lipid or necrotic core, and in the vascular endothelium." (PMID 36362423, 2022). "The objective of this study was to analyze the associations between two enzymes –MPO and PON-1 and type 2 diabetes (T2DM) in patients with ischemic heart disease (IHD)." (PMID 36463116, 2022). "The objective of our study was to analyze the associations between type 2 diabetes and the concentration of two enzymes – myeloperoxidase and paraoxonase-1 in patients with ischemic heart disease." (PMID 36463116, 2022). "There was a positive correlation between serum MPO concentration and the presence of coronary heart disease, and also with its severity." (PMID 34821692, 2021). "Clinical trials have correlated high circulatory MPO levels with the mortality in patients with coronary artery diseases, acute ischemic stroke, and heart failure (HF)." (PMID 35052529, 2021). "Further studies have found that MPO concentration is correlated with the severity of coronary stenosis in patients with coronary heart diseases." (PMID 33410147, 2021). "The release of myeloperoxidase (MPO) by activated neutrophils in the setting of inflammation has been associated with atherosclerotic diseases, namely coronary artery disease and its most grievous manifestation, acute coronary syndrome." (PMID 34681830, 2021). "Neutrophils are also used as predictive cells in coronary heart diseases and their specific marker, myeloperoxidase (MPO), is reliable when used for discriminating AMI patients." (PMID 30898123, 2019). "In accordance, elevated level of MPO-DNA complex, the marker of NETosis, correlated with the severity of coronary artery diseases." (PMID 31447863, 2019). "An elevated myeloperoxidase concentration is documented in various studies of coronary artery diseases, indicating the prognostic significance of myeloperoxidase in these conditions." (PMID 31750312, 2019). "In patients with coronary artery disease (CAD), double-stranded DNA, nucleosomes, citrullinated histone H4, and myeloperoxidase–DNA complexes, have been shown to positively associate with formation of thrombin-antithrombin complexes." (PMID 30992036, 2019). "Previous studies reported that elevated derivatives of reactive oxygen metabolites and myeloperoxidase correlated with NLR in patients with coronary artery disease." (PMID 30942116, 2019). "MPO is a biomarker of neutrophil activation and inflammation following strenuous exercise and is systemically elevated in patients with coronary artery disease." (PMID 30200480, 2018). "Circulating MPO also shows a link with red blood cells (RBCs)’ rigidity index in several patients with combined ischemic heart disease." (PMID 29669993, 2018). "In the past, autopsy studies revealed increased levels of cells containing myeloperoxidase (MPO) at the site of instable plaque rupture in patients who died as a result of severe coronary artery disease." (PMID 29970802, 2018).
coronary artery disease (continued). "Myeloperoxidase is now considered as a new biomarker of inflammation in these diseases as well as other ailments like ischemic heart disease and acute coronary syndrome." (PMID 29669993, 2018). "Elevated levels of circulating MPO are observed in patients with coronary artery diseases, unstable angina, and acute myocardial infarction." (PMID 29669993, 2018). "The authors also found MPO to be related to coronary artery disease and thus explained the relation of MPO with mortality." (PMID 28916973, 2017). "In fact, a recent study regarding the use of MPO as a biomarker for inflammation in ischemic heart disease suggested that, with new commercial methods, it is feasible to measure MPO at a low cost and high volume." (PMID 28286723, 2017). "In a cross sectional cohort of 282 suspected coronary artery disease subjects, dsDNA, nucleosomes, citrullinated histone H4 and myeloperoxidase complexes were found to be significantly elevated and positively correlated with thrombin generation." (PMID 27811985, 2016). "There are studies reporting a relationship between elevated MPO activity and the severity of coronary artery disease." (PMID 27598133, 2016). "Myeloperoxidase is a hemoprotein that abundant in rupture plaques and useful as a clinical tool in coronary artery disease (CAD), however it is inferior to CRP as a marker for risk stratification." (PMID 25237354, 2014). "MPO-modified apoA-I is localized to atherosclerotic lesions and is detectable in the plasma of coronary artery disease patients." (PMID 24015188, 2013). "The leukocyte enzyme myeloperoxidase (MPO) is secreted during acute inflammation and causes oxidation of lipoproteins that is linked with the presence of coronary disease." (PMID 22708908, 2012). "Activated polymorphonuclear neutrophils, an early event in unstable coronary disease, liberate MPO, which has oxidative power." (PMID 19079718, 2008). "Therefore, this study aimed to investigate the relationship between serum MPO levels and coronary artery disease." (PMID 38383869, 2024). "Four of them (CLDND1: Claudin Domain Containing 1, AHRR: Aryl Hydrocarbon Receptor Repressor, MPO: Myeloperoxidase, and PTCD2: Pentatricopeptide Repeat Domain 2), involved in lipid metabolism and inflammatory diseases, were associated with coronary heart disease." (PMID 37190071, 2023). "In summary, while the role and evidence for MPO in HF is not as robust as in coronary heart disease, MPO is a potentially useful clinical diagnostic and prognostic biomarker for HF." (PMID 36979896, 2023). "In addition, clinical studies strongly indicate that the plasma concentrations of MPO are associated with the occurrence and severity of coronary artery diseases; patients with coronary artery diseases exhibit significantly high MPO concentrations." (PMID 36550471, 2022). "Several investigations have revealed a link between MPO levels and coronary artery disease." (PMID 35815198, 2022). "Over the decades, MPO has been suggested to be used as a powerful diagnostic and prognostic marker for a wide variety of CVD conditions, such as acute myocardial infarction (AMI), coronary artery disease (CAD), and congestive HF." (PMID 35740071, 2022). "Furthermore, most studies investigated only the total MPO levels, but rarely the MPO activity at the same time in coronary heart disease patients with T2DM." (PMID 36404308, 2022). "On the other hand, many studies show that in patients diagnosed with unstable coronary artery disease, plasma MPO concentrations are much higher than in control groups, and this would suggest an inverse relationship between MPO concentration and the presence of rupture plaques in arteries." (PMID 35743980, 2022). "Some studies have suggested that elevated MPO levels predict future risk of coronary artery disease in apparently healthy individuals, but some do not." (PMID 36404308, 2022).
coronary artery disease (continued). "Increased oxTrp72-apoA1 levels were correlated with an increased coronary artery disease risk and cardiovascular risk, even after adjusting for traditional CVD risk factors, i.e., apoA1, MPO, and high sensitivity C-reactive protein levels, and lipid lowering medication use." (PMID 36362423, 2022). "Furthermore, a recent study has suggested that HDL-associated enzymes, paraoxonase 1 and myeloperoxidase (MPO), are potential indicators of dysfunctional HDL and risk the stratification of coronary heart disease." (PMID 32357465, 2020). "The activity of myeloperoxidase (MPO), stored in azurophilic granules of neutrophils and released during inflammation, has been shown to be increased in the plasma of patients with diabetes concomitant with coronary heart disease." (PMID 30443223, 2018). "Furthermore, a correlation has been reported between plasma MPO concentration and red blood cell rigidity index in type-2 diabetes patients with coronary heart disease." (PMID 27007571, 2016). "MPO is often used as an inflammatory marker for early detection of several diseases including urinary tract infection, ischemic heart disease and acute coronary heart syndrome, and cardiovascular risk in prepubertal obese children and in patients with type 2 diabetes." (PMID 27274868, 2016). "Furthermore, since higher myeloperoxidase levels were reported in Apo−/− mice, we can postulate that C2238/αANP may, at least in part, associate to higher myeloperoxidase levels, as previously reported in coronary artery disease patients, through its ability to lower ApoE gene expression." (PMID 26720342, 2015). "The observation that myeloperoxidase is involved in oxidative stress and inflammation has been a leading factor to study myeloperoxidase as a possible marker of plaque instability and a useful clinical tool in the evaluation of patients with coronary heart disease." (PMID 18382609, 2008). "Unraveling myeloperoxidase’s (MPO) correlation with coronary artery disease (CAD) and genetic variations, this study seeks to enhance diagnostic precision and therapeutic strategies." (PMID 38383869, 2024). "MPO could also predict long-term mortality in patients with coronary disease." (PMID 34821692, 2021). "Myeloperoxidase (MPO) (produced and secreted by leukocytes) is an enzyme produced by polymorphonuclear leukocytes and has atherogenic and pro-oxidant effects on cardiac tissue leading to its association with increased risk of coronary artery disease and acute HF." (PMID 34540917, 2021). "Therefore, we investigated whether salivary levels of MMP-9 and MPO corresponded to plasma levels in patients with coronary artery disease (CAD), both at rest and after acute physical exercise." (PMID 30726210, 2019). "Recent studies show that there is a specific interaction between MPO, apoAI, and PON1 on the surface of HDL and that the MPO/PON1 ratio could be a potential indicator of dysfunctional HDL and, thus, be used for risk stratification in coronary artery disease." (PMID 28611100, 2017). "Within the context of investigating genetic variations within the Myeloperoxidase (MPO) gene, a cohort of 11 individuals, comprising both controls and patients diagnosed with coronary artery disease (CAD), was meticulously studied." (PMID 38383869, 2024). "Several studies have shown a strong correlation between MPO and CVD, including coronary artery disease, congestive heart failure and stroke." (PMID 38502586, 2024). "It has also been shown that lipoprotein carbamylation catalyzed by myeloperoxidase (MPO) facilitates many atherosclerotic activities and, thus, may be a mechanism linking inflammation and coronary artery disease." (PMID 40241896, 2025). "Moreover, aspirin, a commonly prescribed medication for individuals with coronary artery disease (CAD), may help explain decreased myeloperoxidase (MPO) levels in CAD patients." (PMID 38383869, 2024).
coronary artery disease (continued). "Since inflammation is thought to play a significant role in the etiology of coronary artery disease, the levels of inflammatory biomarkers, such as IL-6, CD40,c-reactive protein (CRP), complement, and myeloperoxidase (MPO), can be used to gauge the severity and prognosis of coronary artery disease." (PMID 38084332, 2023). "Elevations of MMP-9 and MPO are in line with previous studies showing high levels of MMP-9 and MPO in obese individuals, and with that they are among the most up-regulated genes in coronary heart disease." (PMID 37430349, 2023). "The presented study shows some of the possible directions for future research to bring us closer to the full understanding of the dysfunctional high-density lipoprotein and the role of myeloperoxidase (MPO) and paraoxonase-1 (PON-1) in patients with ischemic heart disease and type 2 diabetes." (PMID 36463116, 2022). "We investigated whether increasing concentration of myeloperoxidase (MPO) and inflammatory markers induce progression and incident acute coronary syndrome (ACS) in stable coronary artery disease (SCAD) patients." (PMID 29618370, 2018). "Use of drugs such as statins, beta-blockers, or ACE inhibitors has been shown to reduce MPO levels in patients with acute coronary syndrome but not in patients with stable coronary artery disease." (PMID 26648662, 2015). "Studies have suggested that MPO, through the modification of LDL, could promote the formation of foam cell and the formation and rupture of the plaque and therefore deserved great attention in understanding the development of coronary artery disease." (PMID 26451069, 2015).